PLAUR (plasminogen activator, urokinase receptor)
Diseases named in the same sentence as PLAUR in open-access papers (continued):
Sharing a sentence is not in itself a finding about the gene and the disease.
glioma (continued). "In conclusion, PLAU and PLAUR could be promising prognostic biomarkers and potential therapeutic targets of glioma patients." (PMID 35087738, 2021). "First, the transcription expression level of PLAU/PLAUR among glioma patients were investigated." (PMID 35087738, 2021). "Some researches had studied CD163, P2RY12 and PLAUR as biomarkers in glioma." (PMID 33408717, 2020). "Thus, PLAUR can modulate macrophage–glioma cell interactions." (PMID 38398231, 2024). "Similar to previous studies, S100A4, PLAUR, and EMP3 were found to be associated with glioma progression to high grade and were identified as the hub genes that may affect TAF infiltration in glioma." (PMID 35574375, 2022). "Moreover, Gene co-expression network analysis enlightens us that immune therapy and specific cancer-related signaling pathway blocking by targeting PLAU/PLAUR might be a new idea for treating glioma." (PMID 35087738, 2021). "Likewise, high expression of PLAUR indicated poor prognosis in all gliomas (p<0.0001)." (PMID 35087738, 2021). "It was observed that TAM cells with high PLAUR expression exhibited increased levels of ICAM-1, OSM, and other molecules known to mediate the MES phenotype of glioma." (PMID 38398231, 2024). "Hence, we deduced that PLAUR could regulate the MES phenotype in glioma tumor cells." (PMID 38398231, 2024). "Functional experiments in vitro with cell lines or primary glioma cells and xenograft models using BALB/c nude mice confirmed the role of PLAUR in promoting the MES phenotype of GBM." (PMID 38398231, 2024). "Among them, ARHGDIB, LRRC25, PLAUR, and TREM1 were selected as prognostic hub genes in lower grade glioma in previous bioinformatic analyses." (PMID 34858984, 2021). "Transcription levels of PLAU and PLAUR were evidently higher in GBM and lower-grade glioma (LGG) than in normal brain tissues." (PMID 35087738, 2021). "PLAUR mRNA expression was significantly increased in Grade III gliomas, compared with Grade II gliomas (p < 0.001), and further increased in Grade IV gliomas/glioblastomas compared with grade III gliomas (p < 0.001)." (PMID 29445239, 2018). "Since no uPAR was detected in the low-grade glioma cell line, we attempted to induce its expression by transfecting the uPAR gene sequence, termed PLAUR." (PMID 40508119, 2025). "Moreover, we confirmed that PLAUR regulated the MES phenotype of GBM through both cell-intrinsic and cell-extrinsic mechanisms involving the modulation of macrophage–glioma interactions." (PMID 38398231, 2024). "Herein, we demonstrate that high levels of PLAUR mRNA expression correlate inversely with patient survival when Grade II, III, and IV gliomas are considered collectively, when glioblastomas are examined, and when only glioblastomas that express a mesenchymal gene expression signature are examined." (PMID 29445239, 2018). "Our analysis was performed with three distinct patient populations to assure that the correlation between high PLAUR mRNA expression and decreased patient survival did not reflect uPAR functioning as an indirect biomarker of glioma grade or a specific subtype of glioblastoma." (PMID 29445239, 2018). "The expressions of PLAU and PLAUR were evidently higher in higher WHO grade, recurrent gliomas, wild type IDH-1 and non-codeletion of 1p19q than their counterparts (p<0.0001)." (PMID 35087738, 2021).
melanoma (64 papers, 1999 to 2025). A malignant, usually aggressive tumor composed of atypical, neoplastic melanocytes. "Correspondently, the plasminogen activator urokinase receptor (PLAUR) gene was inactivated by the double-nickase Cas9 system in human melanoma A375p cells, by transfection with nCas9 and two PLAUR-gRNAs plasmids." (PMID 36139356, 2022). "Hypoxia can promote lymph node metastasis via up-regulation of PLAUR, and up-regulation of HIF1a, JUN and PLAUR in our invasive cell lines hints at possible activation of JUN/AP1 and HIF/ARNT pathways in melanoma." (PMID 20041153, 2009).
prostate carcinoma (54 papers, 2005 to 2026). A carcinoma that arises from epithelial cells of the prostate gland. "For example, elevated levels of urokinase plasminogen activator and its receptor involved in extracellular matrix degradation and encoded by PLAU and PLAUR are positively correlated with prostate cancer progression and metastasis." (PMID 39741355, 2024).
colon carcinoma (41 papers, 2003 to 2026). "used CRISPR/Cas9 gene to knock out the uPAR-encoding gene PLAUR in colon cancer cells, resulting in immature mitochondrial development, decreased glycolysis, and increased lactate secretion." (PMID 37020597, 2023). "Increased expression of PLAUR and components of the plasminogen activation system correlate with malignancy and are associated with metastasis in several types of cancer, including colon cancer (61, –, 64)." (PMID 28717003, 2017). "Significant survival differences between patients with high and low PLAUR expression were observed for patients with lung and colon cancer." (PMID 36124441, 2023). "Besides, the dysregulation of PLAUR is involved in the progression of colon cancer and gefitinib resistance of non-small cell lung cancer." (PMID 35111196, 2021). "Interestingly, FOXM1 transactives PLAUR expression to promote colon cancer progression and metastasis." (PMID 27259253, 2016). "Receptor targets of SLURP1, such as α7-nAChRs, Plasminogen Activator, Urokinase Receptor (PLAUR), Plasminogen Activator, Urokinase (PLU), and choline acetyltransferases are significantly expressed in primary colon tumors." (PMID 37896222, 2023). "A significant overlap was detected with several relevant gene families, including colon cancer progression (e.g., FN1, IGBP3, PLAUR and TIMP1; P=0.00052), tumour cell apoptosis (e.g., BID, TNFRSF21, PHLDA1 and NOTCH1; P=1.46 × 10–6) and cell proliferation (e.g., CTGF, SPP1, FOLR1 and SPARC)." (PMID 21119668, 2010).
glioblastoma (41 papers, 2008 to 2026). The most malignant astrocytic tumor (WHO grade IV). "PLAUR has been shown to promote glioblastoma NS cell survival and is associated with a more aggressive mesenchymal subtype of glioblastoma tissue." (PMID 36231068, 2022). "By mining large TCGA datasets, we demonstrated that high levels of PLAUR mRNA expression are associated with a worsened prognosis in glioblastoma." (PMID 29445239, 2018). "PLAUR encodes the urokinase receptor (uPAR), which promotes cell survival, migration, and resistance to targeted cancer therapeutics in glioblastoma cells in culture and in mouse model systems." (PMID 29445239, 2018). "PLAUR can promote cell survival, migration and resistance to targeted cancer therapeutics in cultured glioblastoma cells, and PLAUR expression is inversely proportional to patient survival." (PMID 33875619, 2021). "Given the correlation between PLAUR mRNA expression and patient survival in glioblastoma, we undertook studies to examine uPAR protein expression in human glioblastomas by immunohistochemistry (IHC)." (PMID 29445239, 2018). "We propose that PLAUR gene expression in glioblastoma adversely affects patient survival by promoting a mesenchymal gene expression profile, by allowing cell survival, and by inducing stem cell-like properties in a small sub-population of glioblastoma cells." (PMID 29445239, 2018). "When PLAUR was over-expressed or silenced in glioblastoma cells, neurosphere growth and expression of mesenchymal subtype biomarkers correlated with uPAR abundance." (PMID 29445239, 2018). "The correlation of PLAUR mRNA expression with decreased patient survival in glioblastoma is particularly interesting because variability in survival in patients with this tumor is small, especially when GCIMP tumors are excluded." (PMID 29445239, 2018). "Several studies have hinted to the importance of IL-1 signaling in pNET microenvironment, while sequencing showed the relevance of CD16, IL-1β and NF-κB signaling pathway, while PLAUR alterations were identified in Glioblastoma and CEACAM8 in cervical small cell neuroendocrine carcinomas." (PMID 39851539, 2025). "Thus, in several distinct model systems, increased PLAUR expression favors the mesenchymal subtype of glioblastoma cell in neurospheres whereas decreased PLAUR expression favors the proneural subtype." (PMID 29445239, 2018). "High levels of PLAUR mRNA in a glioblastoma tissue sample may be observed if the density of uPAR-immunopositive cells is high." (PMID 29445239, 2018). "Indirectly, through its effects on PLAUR gene expression, hypoxia may favor transitioning of glioblastoma cells towards the mesenchymal subtype." (PMID 29445239, 2018). "Immunohistochemical analysis of human glioblastomas showed that uPAR is typically expressed by a small sub-population of the cancer cells; it is thus reasonable to conclude that this subpopulation of cells is responsible for the effects of PLAUR on patient survival." (PMID 29445239, 2018). "To determine how PLAUR expression in a small sub-population of glioblastoma cells may influence tumor aggressiveness, we studied glioblastoma cells in neurosphere culture." (PMID 29445239, 2018). "To identify pathways by which PLAUR gene expression in occasional tumor cells may affect patient survival, we examined glioblastoma cells in neurospheres, which select for multipotent cells with cancer stem cell-like properties." (PMID 29445239, 2018). "In immunohistochemistry (IHC) studies of human glioblastomas, uPAR was robustly expressed by a small sub-population of the cancer cells, suggesting that the effects of PLAUR expression on patient survival in glioblastoma may reflect the activity of uPAR in a sub-population of the cancer cells." (PMID 29445239, 2018). "Furthermore, these results suggest that the correlation between PLAUR mRNA expression and patient survival in glioblastoma may reflect the activity of uPAR protein in a small sub-population of the cancer cells." (PMID 29445239, 2018).
glioblastoma (continued). "The effects of regulating PLAUR gene expression in TS-543, GSC-23, and U87 cells suggest that the glioblastoma gene expression signature and subtype may be regulated at the cellular level." (PMID 29445239, 2018).
pancreatic cancer (40 papers, 1997 to 2026). "For example, FOXM1c is upregulated in pancreatic cancer which, as a transcription factor, has binding sites within the PLAUR promoter and causes the upregulation of PLAUR, ultimately affecting the migration of pancreatic cancer cells." (PMID 35864968, 2022). "LY6D, LY6E, PSCA, and PLAUR, known markers tumorigenesis and cancer cell maintenance, were significantly associated with lower overall survival outcome in our pancreatic cancer analysis." (PMID 33613843, 2021).
gastric cancer (37 papers, 2006 to 2025). A primary or metastatic malignant neoplasm involving the stomach. "Comprehensive evaluation of metastasis and invasion pathway identified a subset of associated genes and confirmed PLAUR and CDH11, both targets of miR-335, to be overexpressed in gastric cancer tissues." (PMID 29075357, 2017). "In gastric cancer, the overexpression of PLAUR has been reported to be closely related to cell invasion and metastasis." (PMID 29075357, 2017). "Among these genes, PLAUR, a validated target of miR-335, significantly increased mRNA levels after knockdown of miR-335 expression in gastric cancer cells." (PMID 29075357, 2017). "Similarly, PLAUR promotes resistance to anoikis and facilitates gastric cancer cell metastasis." (PMID 38460046, 2024). "In gastric cancer, exogenous miR-335 decreased migration and invasion of AGS and Hs 746T cells by inhibiting PLAUR and CDH11 genes." (PMID 32974144, 2020). "Our comprehensive evaluation of metastasis and invasion pathway led us to identify and confirm that PLAUR, a validated target of miR-335, and CDH11 are overexpressed in gastric cancer tissues." (PMID 29075357, 2017).
lung carcinoma (37 papers, 1998 to 2025). "In the TCGA lung cancer cohort, PLAUR mRNA expression was significantly associated with shortened PFS in both univariate and multivariate analyses." (PMID 36124441, 2023). "Upregulation of PLAUR mRNA expression was significantly associated with shortened PFS only in lung cancer." (PMID 36124441, 2023). "In TCGA cohort, association of PLAUR gene expression with shortened PFS was found only in patients with lung cancer." (PMID 36124441, 2023). "Moreover, we found that EGFR is one of the potential target proteins of PLAUR, which is one of the most common mutation targets in lung cancer." (PMID 36091160, 2022). "Obtained results clearly demonstrate the importance of mentioned regulators for LUAD/LUSC progression: it was shown that up-regulation of PTX3, TIMP1, SERPINE1, and PLAUR not only on mRNA, but also on protein level was significantly associated with poor survival in patients with lung cancers." (PMID 34807957, 2021). "High PLAUR gene expression conferred significant survival disadvantage only in patients with colon and lung cancer." (PMID 36124441, 2023). "However, TCGA subgroup survival analysis has demonstrated that PLAUR mRNA expression significantly predicts PFS only in lung cancer patients, which potentially alludes to suPAR bearing predictive ability for PFS specifically in this cancer type." (PMID 36124441, 2023). "Therefore, association of lung cancer with smoking exposure may partly explain findings of highest suPAR√ levels and PLAUR mRNA expression in lung cancer patients." (PMID 36124441, 2023). "The results also showed that the expression levels of PLAUR and SEMA3A were significantly upregulated in the lung cancer tissues." (PMID 36091160, 2022). "IHC staining also confirmed that HNRNPAB, PLAUR, and SEMA3A protein expressions in lung cancer specimens were significantly increased, which supported our hypothesis." (PMID 36091160, 2022). "Overlapping these gene sets revealed that 4 genes (PTX3, TIMP1, SERPINE1, and PLAUR) are common to both LUSC and LUAD patients, which may indicate the universality of these markers for the occurrence of lung malignant neoplasms." (PMID 34807957, 2021). "Finally, considering the identified association of ALI-specific key genes with poor prognosis in LUAD/LUSC patients, TIMP1, SERPINE1, PLAUR, and PTX3 may be used as marker genes to control the severity of lung cancer progression in the case of accompanying pulmonary inflammation." (PMID 34807957, 2021).
ovarian carcinoma (37 papers, 2003 to 2025). A malignant neoplasm originating from the surface ovarian epithelium. "Ovarian cancer patients, especially those in the advanced stage, often exhibit increased serum levels of PLAU and PLAUR, but while its elevated level is linked to shorter progression-free and overall survival, it does not represent a standalone prognostic indicator." (PMID 38031074, 2023). "From the analysis performed on the probable miRNAs with an affinity for PLAUR 3’UTR, only miR-328-3p was reported to play stem-related functions maintaining CSC properties in ovarian cancer and enhancing metastasis via the downregulation of the DNA damage binding protein 2 (DDB2)." (PMID 34055629, 2021).
colorectal cancer (30 papers, 2007 to 2025). A primary or metastatic malignant neoplasm that affects the colon or rectum. "Analysis of correlation of all detected transcription factors with ITGA5 and PLAUR in the colorectal cancer samples from TCGA revealed six genes with significant correlation." (PMID 34858489, 2021). "For example the plasminogen activator and urokinase receptor PLAUR/UPAR is frequently overexpressed in ovarian and colorectal cancers, where it facilitates cell motility and metastatic potential and emerges as a marker of malignancy." (PMID 24548329, 2014). "PLAUR is involved in cellular movement and metastasis and expression increases during the critical transition from severe dysplastic adenoma to invasive carcinoma in colorectal cancer." (PMID 25079072, 2014). "Moreover, we identified some diseases and phenotypes related to HNRNPAB/PLAUR/SEMA3A from the database, including non-small cell lung carcinoma (NSCLC), colorectal carcinoma (CRC) and LUAD (disorder)." (PMID 36091160, 2022). "Next, we analyzed expression correlation for these transcription factors, ITGA5, and PLAUR in the mRNA-sequencing data of colorectal cancer samples from TCGA to find regulators which expression significantly correlates with both ITGA5 and PLAUR in the samples of intestinal origin." (PMID 34858489, 2021).
liver fibrosis (23 papers, 2012 to 2026). "Nevertheless, a recent article demonstrated that elimination of senescent HSCs by generating CAR‐T cells directed against PLAUR, a cell surface marker of senescent cells, decreases liver fibrosis upon a Western diet." (PMID 37667516, 2023).
osteosarcoma (23 papers, 2006 to 2025). A usually aggressive malignant bone-forming mesenchymal neoplasm, predominantly affecting adolescents and young adults. "PLAUR, which encodes for uPAR, has been shown to drive tumor proliferation and metastasis in multiple cancer types including pediatric rhabdomyosarcoma and osteosarcoma." (PMID 38810090, 2024). "EGFR and PLAUR expression was also evaluated in 51 canine hemangiosarcomas and 31 canine osteosarcomas." (PMID 29218302, 2017). "Expression of both EGFR and PLAUR genes was detectable in all canine sarcomas, with hemangiosarcoma having higher levels of PLAUR mRNA, and hemangiosarcoma and osteosarcomas having approximately equivalent levels of EGFR mRNA, which paralleled results in human sarcomas." (PMID 29218302, 2017).